MRPL1 (mitochondrial ribosomal protein L1)
Synonyms: L1mt; MRP-L1; BM022; uL1m
Tractability: Small molecule: a structure with a bound ligand is known. PROTAC: ubiquitination databases record sites on it; its protein half-life has been measured.
Gene: Protein-coding gene on chromosome 4 (77,862,826 to 77,952,791, forward strand). Ensembl gene ENSG00000169288.
Subcellular location: Mitochondrion
Subcellular location (Human Protein Atlas): Mitochondria
Pathways (Reactome):
Metabolism of proteins: Mitochondrial ribosome-associated quality control; Mitochondrial translation elongation; Mitochondrial translation initiation; Mitochondrial translation termination
Gene Ontology:
Molecular function: protein binding; RNA binding; structural constituent of ribosome
Biological process: mitochondrial translation; regulation of translation; translation
Cellular component: mitochondrion; mitochondrial inner membrane; mitochondrial large ribosomal subunit; large ribosomal subunit
Genetic constraint (gnomAD): Loss-of-function variants: 6 observed, 11.93 expected, observed/expected ratio (o/e) 0.5, 90% interval 0.27 to 0.99. The upper end of that interval is the gene's LOEUF score, 0.99, which puts it in group 4 of 6, group 1 being the genes least tolerant of losing a copy. Missense variants: 171 observed, 170.97 expected, observed/expected ratio (o/e) 1, 90% interval 0.88 to 1.13. Synonymous variants: 57 observed, 60.94 expected, observed/expected ratio (o/e) 0.94, 90% interval 0.75 to 1.17.
Homologues: Orthologues: chimpanzee MRPL1 (100% identical), rabbit MRPL1 (84% identical), guinea pig MRPL1 (80% identical), mouse Mrpl1 (78% identical), rat Mrpl1 (76% identical), tropical clawed frog mrpl1 (40% identical), zebrafish mrpl1 (40% identical).
Diseases named in the same sentence as MRPL1 in open-access papers:
MRPL1 is named in the same sentence as 9 diseases in open-access papers, as found by Europe PMC text mining. Sharing a sentence is not in itself a finding about the gene and the disease. The quoted sentences say what the papers report.
colorectal cancer (2 papers, 2024 to 2025). A primary or metastatic malignant neoplasm that affects the colon or rectum. "One study found that MRPL37 is associated with metastasis inhibition in colorectal cancer, with interactions between MRPL37 and SLC25A10 through MRPL1 reinforcing its synergistic role." (PMID 41399509, 2025). "Conversely, a broad investigation into metastasis-associated genes in colorectal cancer proposed that MRPL19 was associated with decreased metastasis risk through SLC25A10 and MRPL1." (PMID 39354291, 2024). "Contrarily, MRPL37 was associated with metastasis inhibition in colorectal cancer, with interactions with SLC25A10 through MRPL1 also identified." (PMID 39354291, 2024). "Though, contrary to the findings in breast and colorectal cancer, the role of MRPL1 in LCLC remains inconclusive." (PMID 39354291, 2024).
lung carcinoma (2 papers, 2021 to 2022). "In lung cancer, genomic profiling identified a distinctive molecular signature in asbestos-exposed patients compared to not-exposed, including copy number aberrations in the 2p16, 9q33.1 and 19p13 loci and MRPL1, INPP4A, SDK and SEMA5B somatic mutations." (PMID 35755315, 2022).
glioma (1 paper, 2021). A benign or malignant brain and spinal cord tumor that arises from glial cells (astrocytes, oligodendrocytes, ependymal cells). "MRPL1 is a part of the gene signature for low-grade gliomas prognosis." (PMID 34795329, 2021).
large cell lung cancer (1 paper, 2024). "MRPL1 has been implicated in the progression of breast, colorectal, and large cell lung cancer (LCLC)." (PMID 39354291, 2024).
tumor (5 papers, 2006 to 2024). "In breast cancer, through the analysis of 1,056 TCGA tumours, increased expression of MRPL1 was associated with poor prognosis and over 50% increased risk of mortality." (PMID 39354291, 2024).
MRPL1 also shares sentences with these, for which no sentence is quoted: breast carcinoma (1 paper); colon cancer (1); lung squamous cell carcinoma (1); malignant mesothelioma (1).